BRCA1 (BRCA1 DNA repair associated)
Diseases named in the same sentence as BRCA1 in open-access papers (continued):
Sharing a sentence is not in itself a finding about the gene and the disease.
breast cancer (continued). "Autosomal dominant germ-line mutations in BRCA1&2 among women are associated with a lifetime risk of 85% for breast cancer and 45% for ovarian cancer." (PMID 29262604, 2017). "As a proof of concept, known breast cancer-predisposing genes like BRCA1, BRCA2, and CHEK2 were selected by our procedure." (PMID 28569218, 2017). "We show that ID cisplatin and PARP-inhibition can successfully ablate mammary epithelial cells, and this approach attenuated tumor onset in a mouse model of Brca1-associated breast cancer from 153 to 239 days." (PMID 28977823, 2017). "Women who are heterozygous for a BRCA1 or BRCA2 pathogenic variant have up to an 80% risk of developing breast cancer by age 90; and an ovarian cancer risk of about 55% with BRCA1 mutations and 25% with BRCA2 mutations." (PMID 28751759, 2017). "A clear example of a preclinical GEMM that has provided mechanistic insight into therapy response and resistance of BRCA1‐mutated breast cancer is the K14cre;Brca1F/F;Trp53F/F (KB1P) mouse model." (PMID 28028012, 2017). "When BRCA1 is mutated and cannot function and therefore the damaged DNA cannot be repaired on time, the risk of breast cancer will greatly increase." (PMID 28359295, 2017). "The identification of BRCA1 mutations and their involvement in breast cancer have gained a lot of attention in the past decade." (PMID 28863181, 2017). "Another recent meta-analysis confer worse overall survival to BRCA1 mutation carriers and worse breast cancer specific survival." (PMID 28985233, 2017). "We found that having Asian ancestry, a prior history of breast cancer, and a BRCA1 or BRCA2 mutation all appear to be positively associated with TNBC." (PMID 28912973, 2017). "The frequency of the four small-range BRCA1/2 Colombian founder mutations was assessed in 1,022 unselected breast cancer patients participating in the Colombian breast cancer case-control study (Col-BCCC) using PCR-based methods." (PMID 28680148, 2017). "‘BRCAness’ breast cancers are sporadic breast cancers that share the same phenotype or traits with BRCA1/2 mutation tumors." (PMID 29152070, 2017). "ID4, upregulated in the offspring of HF diet-fed dams, is associated with poor prognosis of breast cancer, inhibits BRCA1 function in basal-like breast cancer, and promotes chemoresistance." (PMID 28673325, 2017). "The TNT study of metastatic or recurrent locally advanced TNBC or BRCA 1/2 mutated breast cancer showed that taxanes and carboplatin were comparably well tolerated in both groups, and that carboplatin was beneficial in BRCA1/2 mutated subgroup." (PMID 29088896, 2017). "TRs were of opposing prognostic significance and silencing of TRalpha appeared to diminish viability of BRCA1 mutated breast cancer cells." (PMID 28427429, 2017). "In these studies, the two Colombian BRCA1 founder mutations accounted for 100% (breast cancer patients) and 92% (ovarian cancer patients) of all BRCA1 mutations." (PMID 28680148, 2017). "Increased in vivo activity was reported with the combination of olaparib and cisplatin compared to single agent alone in a BRCA1-deficient breast cancer mouse model." (PMID 29108297, 2017). "We identified for the first time that β-hCG expression is linked to BRCA1 status and its overexpression is seen in BRCA1 mutated breast cancer cells, BRCA1 conditional knockout mouse breast cancer tissues and BRCA1 floxed basal cell carcinoma (BCC) tissues." (PMID 28869585, 2017). "In early studies, oophorectomy was associated with breast cancer risk reduction of approximately 50%, but recent findings call into question the benefit of oophorectomy for the prevention of premenopausal breast cancer in BRCA1 mutation carriers." (PMID 28624978, 2017).
breast cancer (continued). "Women carrying mutations in BRCA1 or BRCA2 show up to 80% of increased risk for developing breast cancer, while men present up to 6%." (PMID 28651617, 2017). "Our results showed a high frequency of BRCA1/2 mutations, especially germline BRCA1 variants, were associated with bilateral breast cancer." (PMID 29152070, 2017). "It is widely accepted that (breast) cancer predisposing mutations (e.g., in BRCA1) are recessive, and that all (normal) cells from a heterozygous mutation carrier are phenotypically identical to the cells of a non-carrier." (PMID 28649653, 2017). "The majority of mutations in BRCA1 or BRCA2 found in Latin-American breast cancer patients are private for each population, with very few mutations shared between countries." (PMID 29088781, 2017). "We report a high expression of β-hCG in BRCA1 mutated breast cancer cell line which was demonstrated in vitro and in vivo." (PMID 28869585, 2017). "The lack of data on possible large-genomic rearrangements (LGRs) in BRCA1/2, and the scarcity of data on the prevalence of BRCA1/2 mutations in Colombian familial and unselected breast cancer patients motivated the present study." (PMID 28680148, 2017). "In summary, our data demonstrated a significant positive association between high nuclear BRCA1 expression and basal cell nature of breast cancer tissues." (PMID 28863181, 2017). "We provided an approximate 5-year risk of breast cancer as 10%, based on her current age and BRCA1 status." (PMID 28780755, 2017). "With ovary cancer, breast cancer is the most known tumor to get BRCA1 or 2 mutations, and is thus a candidate for PARPi radiosensitization." (PMID 28978184, 2017). "Olaparib was already shown to be effective in breast cancer treatment, but now we also demonstrate the prophylactic effect of systemic PARP-inhibition in Brca1-associated breast cancer." (PMID 28977823, 2017). "Elucidation of the role of MTHFR as a modifier gene in familial breast cancer is of particular relevance in South Africa, given the high frequency of founder BRCA1/2 mutations in Afrikaner, Coloured and Xhosa breast cancer patients." (PMID 28241424, 2017). "Mutation detection accuracy was affected by the choice of primer handling approach based on real NGS datasets of 7 human peripheral blood or breast cancer tissue samples with known BRCA1/BRCA2 mutations and >130000 simulated NGS datasets with unique mutations." (PMID 28484262, 2017). "We analyzed a large cohort of breast cancer patients identified as having one or more pathogenic or likely pathogenic (P/LP) variants in genes other than BRCA1/2." (PMID 28766213, 2017). "We recently highlighted thyroid hormone receptors (TRs) to be widely expressed in breast cancer tissue deriving from patients diagnosed with a BRCA1 germline mutation." (PMID 28427429, 2017). "Among our French Canadian cohort, 24% of high-risk breast cancer families were found to be carriers of a deleterious BRCA1 or BRCA2 mutation." (PMID 29108258, 2017). "Our data suggests that BRCA2 p.Ile3412Val is likely to be benign and BRCA1 p.Arg762Ser is likely to be associated with breast cancer risk." (PMID 28222693, 2017). "Our initial GWAS had identified SNPs associated with decreased (ZNF423) and increased (CTSO) risk for breast cancer occurrence, both of which appeared to regulate BRCA1." (PMID 28968398, 2017). "Family history of breast cancer was associated with lower BRCA1 H-score with a higher fraction of BRCA1 protein is located in the nucleus (N/C ratio: positive family history = 3.8; no family history = 1.4; p = 0.001)." (PMID 28863181, 2017). "RANKL-driven progesterone signaling has been shown to play a critical role in breast cancer tumorigenesis in BRCA1 mutation carriers." (PMID 28624978, 2017). "In short, a combination of ID cisplatin with systemic olaparib increases tumor-free latency in a mouse model of Brca1-associated breast cancer." (PMID 28977823, 2017).
breast cancer (continued). "This is the first study to implement the DCE methodology to provide a clear picture of the preferences among women with BRCA1/2 mutations regarding the attributes of different options to reduce their risk of breast cancer." (PMID 28624978, 2017). "Studies of breast cancer patients and early population-based screening studies suggest that between 10% and 15% of women with a substantial family history likely carry BRCA1/2 mutations, and about half of BRCA mutation carriers are unaware of this status." (PMID 28340626, 2017). "Recent studies demonstrate that genetic predispositions for familial breast cancer can be ethnic-specific, as well exemplified by the different spectrum of germline mutation in BRCA1 and BRCA2 between different ethnic populations." (PMID 28076423, 2017). "Monitoring BRCA1 gene mutations has proven to be useful for breast cancer risk assessment and therapeutic decision-making." (PMID 29156836, 2017). "In a BRCAness profile, each gene was assigned a weight based on the difference in expression it exhibits between BRCA1/2-mutated familial from sporadic breast cancer samples." (PMID 29146938, 2017). "Within breast cancer patients, approximately 10% are heterozygous mutation carriers of the BRCA1/BRCA2/PALB2 gene, and their cancer resulted from the loss of heterozygosity." (PMID 29023372, 2017). "Inherited breast cancer is caused by penetrant susceptibility genes and most often involves germ line mutations of the BRCA1 and BRCA2 genes in about 15% of familial breast cancer patients." (PMID 28741261, 2017). "The presence of germline mutations in BRCA1/2 increases the lifetime risk of breast cancer to 60–70% and occurs in about 10% of patients with TNBC." (PMID 28454587, 2017). "Hereditary harmful BRCA1 mutations have been linked with an increased risk of developing breast cancer." (PMID 29156836, 2017). "While, a few gene mutations such as breast cancer gene 1 and 2 (BRCA1/2) instigate up to 25% breast cancer and also responsible for the highest number of mortalities." (PMID 28477017, 2017). "Probably this is the reason why only some of the breast cancer tissues express β-hCG24, 25 in a BRCA1 defective or BRCA1 deficient such as BRCA1 hyper-methylated condition." (PMID 28869585, 2017). "Breast cancer is the major cause of cancer death among the female worldwide, gene BRCA1 and FGF22 are enriched in this pathway." (PMID 29170526, 2017). "The overall mutation-positive rate for breast cancer susceptibility genes for patients with prior BRCA1/2 testing reported was 7.6% (N = 12/158), with 1 patient carrying mutations in two different breast cancer genes." (PMID 28008555, 2017). "The mutated tumor suppressor gene, PALB2 largely affects BRCA2, which increase the risk of BRCA1/2 based breast cancer." (PMID 28477017, 2017). "Efforts have been made to study genetic predisposition for Egyptian familial breast cancer, mostly focused on BRCA1 and BRCA2, but comprehensive data at genomic level from local patients are lacking." (PMID 28076423, 2017). "We next investigated the preventive effect of ID cisplatin in a mouse model for BRCA1-associated human breast cancer." (PMID 28977823, 2017). "Anytime use of diagnostic chest X-rays before the age of 50 years in women carrying the BRCA1/2 gene mutations is associated with an increased risk of breast cancer (BRCA1 OR = 1.16; 95% CI = .64–2.11; BRCA2 OR = 1.22; 95% CI = .62–2.42)." (PMID 28865460, 2017). "Approximately 10% of these cases are likely to be hereditary, and roughly 40–50% of hereditary breast cancer cases are attributed to mutations in BRCA1 gene." (PMID 28863181, 2017). "An example is represented by breast cancers BRCA1/2-mutated and some sporadic TNBC that have DNA repair defects, and they are sensitive to DNA-damaging drugs like platinums and Poly (ADP-ribose) polymerase (PARP) inhibitors." (PMID 28491135, 2017).
breast cancer (continued). "The 10-year breast cancer risk in women with BRCA1/BRCA2-associated ovarian cancer was 11%, compared to 28% in the control group (mortality rates at five and ten years were 33% and 61%, respectively)." (PMID 28780755, 2017). "A small number of studies have indicated that breast cancer risk is lower in BRCA1/BRCA2 mutation carriers after an ovarian cancer diagnosis, compared to unaffected mutation carriers." (PMID 28780755, 2017). "AZD2281, a PARP inhibitor, resulted in progression free survival of approximately six months in patients with BRCA1- or BRCA2-deficient advanced breast cancer (of which 50% were triple-negative)." (PMID 29190901, 2017). "Previously reported cumulative risks of breast cancer for BRCA1 mutation carriers vary largely between studies, with an average cumulative risk of 65%2." (PMID 28680148, 2017). "BRCA1 deficiency is associated with the genesis of breast cancers that are genomically unstable and typically display a basal-like transcriptome, thus resembling the cells that constitute the outer “basal” layer of the normal adult human mammary gland." (PMID 28427147, 2017). "The landscape of mutations in the BRCA1/2 genes has been extensively studied and the relationship between the mutations and breast cancer risk is also well-defined." (PMID 29872710, 2017). "GTF2H2 (5q13.2) is a transcription factor with a role in the nucleotide excision repair (NER) pathway, a DNA repair pathway that is disrupted in BRCA1-associated breast cancers." (PMID 28145423, 2017). "The rs11540855 SNP is in high LD (r2 = 0.90) with the breast cancer-associated GWAS SNP rs8170, which was first found as a modifier of breast cancer risk in BRCA1 mutation carriers." (PMID 28957321, 2017). "Taken the breast cancer-susceptible gene BRCA1 as an example, genetic BRCA1 mutations were significantly more common in Jewish (10.2%) versus non-Jewish (2.0%) cases." (PMID 28393072, 2017). "One of the potential mechanisms for breast cancer susceptibility due to BRCA1 mutations is by alterations in cellular metabolism." (PMID 28369883, 2017). "A study among newly diagnosed breast cancer patients carrying a BRCA1/2 mutation demonstrated that physicians’ recommendations influenced their decision to undergo a contralateral prophylactic mastectomy." (PMID 28570656, 2017). "Since our previous study had identified ZNF423 and CTSO SNPs that were associated with breast cancer risk, both of which appeared to regulate BRCA1, we examined their joint effect on cell proliferation in the presence of tamoxifen or E2 treatment." (PMID 28968398, 2017). "The three main breast cancer PRSs that were constructed on the basis of associations with female breast cancer risk were strongly associated with male breast cancer risk for both BRCA1 and BRCA2 mutation carriers." (PMID 28448241, 2017). "Even with a combined pathology adjusted Manchester score of 20 or higher indicating at least a 20% likelihood of a BRCA1/2 mutation only 5/33 (15%) women with HER2+ breast cancer had a mutation identified." (PMID 27796713, 2017). "Carriers of mutations in the BRCA1- or BRCA2 gene (breast cancer genes) have a substantially increased risk of both breast and ovarian cancer." (PMID 28096903, 2017). "In case of a moderately or highly increased breast cancer risk, periodic surveillance of those with an increased risk is recommended and/or preventive surgery for carriers of a BRCA1/2 gene mutation." (PMID 28083845, 2017). "For unaffected women, assessment of breast cancer risk and BRCA1/2 probability should take into account the pathology of the most relevant close relative." (PMID 27796713, 2017). "Triple-negative (TN) breast cancer (BC) shares histological characteristics with germline BRCA1 mutation-associated tumours." (PMID 29259228, 2017). "Although hereditary mutations in BRCA1 gene are associated with familial breast cancer, the majority of the mammary carcinomas present sporadic occurrence." (PMID 28945747, 2017).
breast cancer (continued). "BRCA1/2 mutations are responsible for 30% of early-onset breast cancers and 90% of family histories of BC and OC." (PMID 27779110, 2017). "In this study, we presented the metabolomic based profile of BC cell lines for the characterization and identification of the breast cancer phenotype linked to the BRCA1 genotype." (PMID 29259228, 2017). "All breast cancer PRSs derived from population-based study results (available online) were statistically significantly associated with breast cancer risks for both BRCA1 and BRCA2 carriers." (PMID 28376175, 2017). "All six ovarian carcinomas and two out of four breast carcinomas available showed a loss of the BRCA1 wild-type allele, which in three out of four ovarian carcinomas analyzed by FISH was associated with duplication of the chromosome 17 containing the variant." (PMID 28186987, 2017). "PRSs that were constructed with SNPs for female breast cancer and prostate cancer in the general population are highly predictive of risk in male carriers of BRCA1/2 mutations." (PMID 28448241, 2017). "The propensity for tumor formation in BRCA1-associated breast carcinomas appears to be driven by specific molecular and cellular alterations triggered by inherited mutations in BRCA1 in breast epithelial differentiation before development of cancer." (PMID 28388533, 2017). "We were unable to see a significant correlation between gene hypermethylation and BRCA1 status but did observe the lowest levels of methylation of all the groups, mirroring the findings seen in BRCA1 associated female breast cancer." (PMID 28893223, 2017). "Whereas BRCA1‐deficient mouse mammary carcinomas showed high sensitivity to the clinical PARP inhibitor olaparib, BRCA1‐deficient metaplastic mammary tumors showed intrinsic resistance." (PMID 28028012, 2017). "Several susceptibility genes have been established for female breast cancer, of which mutations in BRCA1 and especially in BRCA2 are also known risk factors for male breast cancer (MBC)." (PMID 28874143, 2017). "History of prior breast cancer was available for 43 cases who were either BRCA1 or BRCA2 mutation carriers." (PMID 27492892, 2016). "Despite its ubiquitous expression, it is thought that BRCA1 mutations increase the susceptibility of developing breast cancer through tissue-specific functions beyond the maintenance of chromosomal integrity." (PMID 27881737, 2016). "We evaluated the entire coding sequence of the HOXB13 gene for germline mutations in 1,250 non-BRCA1/2 breast cancer patients and 800 controls from the Rotterdam Breast Cancer Study (RBCS) study." (PMID 27424772, 2016). "In conclusion, for the first time we have identified that NEAT1 plays oncogenic roles in promoting tumorigenicity and stemness of BRCA1-deficient breast cancer." (PMID 27556296, 2016). "In patient P0013, a germline mutation in BRCA1 (p.W1712fs) was identified that confer increased breast cancer susceptibility." (PMID 27245685, 2016). "Genetic predisposition can be the cause of breast cancer and germline mutations in the two major breast cancer susceptibility genes BRCA1 and BRCA2 confer highly elevated risk of the disease." (PMID 27357824, 2016). "Taking into account a high disease penetrance in carriers of BRCA1 mutation, it seems reasonable to recommend inclusion of the 5382insC mutation test in future research on the development of screening programs for breast cancer prevention in Uzbekistan." (PMID 29138730, 2016). "Patients harboring inactivating mutations in BRCA1 or BRCA2 are at an increased risk of developing breast cancer." (PMID 27323902, 2016). "In conclusion, proteome profiling of secretome using murine breast tumor models is a powerful strategy to identify non-invasive candidate biomarkers of BRCA1-deficient breast cancer." (PMID 27566577, 2016). "Recently, we provided direct genetic evidence for the role of RANK/RANKL in Brca1 mutation-driven breast cancer." (PMID 27881737, 2016).